HMGB2 (high mobility group box 2)
Diseases named in the same sentence as HMGB2 in open-access papers (continued):
Sharing a sentence is not in itself a finding about the gene and the disease.
Stroke (1 paper, 2021). Sudden impairment of blood flow to a part of the brain due to occlusion or rupture of an artery to the brain. "But the function and underlying mechanisms of Hmgb2 in stroke remain unclear." (PMID 34094642, 2021). "This study has reported a discovery that Hmgb2 acts as a microglia activator and mediates microglia pro-inflammatory and immune response in stroke." (PMID 34094642, 2021). "To explore the expression of Hmgb2 in the microglia after stroke, we co-stained Hmgb2 with Iba1 by immunofluorescence at 3days after stroke." (PMID 34094642, 2021). "We demonstrated that Hmgb2 is primarily expressed in microglia and mediates microglia pro-inflammatory response after stroke." (PMID 34094642, 2021). "Our present findings reveal a plausible explanation that stroke induces Hmgb2 expression in microglia and initiates microglia pro-inflammatory response including the expression and secretion of Ctss onto the extracellular space in the brain." (PMID 34094642, 2021). "In the present study we have shown that Hmgb2 activates Ctss transcription and induces Ctss expression in microglia of stroke mice." (PMID 34094642, 2021). "Ctss was mainly expressed in microglia and the transcriptional level of Ctss after stroke was correlated with the expression of Hmgb2." (PMID 34094642, 2021). "Western blots of the lysates from microglia showed that the levels of Hmgb2 in stroke mice were elevated by more than 6-fold of sham controls (0.17 ± 0.024 in sham versus 1.02 ± 0.13 in stroke group, mean ± SEM, n = 5 mice/per group, p = 0.0021, t-tests)." (PMID 34094642, 2021). "Together, we report that Hmgb2 and Ctss as the major microglia inflammatory response mediators in different stages of stroke and hence warrants the promising targets for stroke therapies." (PMID 34094642, 2021). "This study uncovers Hmgb2 and Ctss as the major microglia inflammatory response mediators in stroke and hence warrants the promising targets for stroke therapies." (PMID 34094642, 2021). "Significantly, Hmgb2 highly expressed in the activated microglia after stroke compared with the sham." (PMID 34094642, 2021). "Inhibition of either Hmgb2 or Ctss blocks microglia pro-inflammatory response and protects against brain damages and improves the neurological functions of stroke mice." (PMID 34094642, 2021). "Inhibition of either Hmgb2 or Ctss blocked microglia pro-inflammatory response and protected against brain damages after stroke." (PMID 34094642, 2021). "We next validated the roles of Hmgb2 in stroke damages.Hmgb2 is a member of high mobility group protein family (Hmgb1-Hmgb4) proteins that influence microglia pro-inflammatory response in some neurological disorders." (PMID 34094642, 2021). "Thus, Ctss as a microglia pro-inflammatory mediator downstream of Hmgb2 contributes to the blood brain barrier dysfunction of stroke." (PMID 34094642, 2021). "Besides, inhibition of Hmgb2 in microglia decreased the content of Ctss at 3 days after stroke operation." (PMID 34094642, 2021). "Thus, Hmgb2 is a promising target for therapeutic intervention of stroke as inhibition of Hmgb2 selectively blocks microglia pro-inflammatory signals blocked while preserving microglia anti-inflammatory functions." (PMID 34094642, 2021). "Thus, Ctss is a pro-inflammatory signal downstream of Hmgb2 and contributes to the blood brain barrier dysfunctions in stroke." (PMID 34094642, 2021). "But, whether Hmgb2 plays roles in stroke damages is yet to be studied." (PMID 34094642, 2021). "Thus, inhibition of either Hmgb2 or Ctss is effective for therapeutic intervention of stroke." (PMID 34094642, 2021). "Microglia were separated from cerebral cortex of the brain after stroke by FACS and lysates from microglia were used to detect the relative expression of Hmgb2 by western blots." (PMID 34094642, 2021).
Stroke (continued). "We found, however, that neither mRNA nor protein of Hmgb1 was changed in microglia of stroke mice, as compared to the controls, indicating that stroke selectively induces the expression of Hmgb2." (PMID 34094642, 2021). "Our data showed that application of Hmgb2-I, but not Hmgb2-SI, knocked down the Hmgb2 expression in microglia after stroke onset as expected." (PMID 34094642, 2021). "A large fraction of these genes such as Hmgb2, TNF and IL-11 were pro-inflammatory factors Cluster two genes such as Ctss and PTPN18are either peptidases or proteases that were expressed at 3 days and peaked 7 days after stroke onset." (PMID 34094642, 2021). "Silencing Hmgb1 gene using a small interference RNA that specifically targets Hmgb1 gene (Hmgb1-I), but not Hmgb2 produced no protective effects on stroke damages." (PMID 34094642, 2021).
thyroid cancer (1 paper, 2020). "The APA modification of HMGB2 may also be involved in thyroid cancer cells." (PMID 32626751, 2020).
transitional cell carcinoma (1 paper, 2020). A malignant neoplasm arising from the transitional epithelium, usually affecting the urinary bladder, ureter, or renal pelvis. "To this purpose, we have screened Y2H libraries, prepared from SKOV-3 cells and from tumor tissue diagnosed as primary transitional cell carcinoma (TCC) of the ovary, with HMGB1 and HMGB2 baits." (PMID 32867128, 2020).
tumor (68 papers, 2013 to 2025). "The study unveiled the underlying mechanisms that HMGB2 boosts tumor growth by dual action on T cells and cancer cells." (PMID 40315321, 2025). "Together, the findings revealed that Hmgb2 deficiency–induced tumor regression depended on STAT1/CXCL10/CXCR3 pathway." (PMID 40315321, 2025). "In HCC, HMGB2 has been associated with poor prognosis and aggressive tumor behavior by altered cell proliferation through antiapoptotic pathways." (PMID 39247201, 2024). "HMGB2 expression is reduced or even completely lost in various tumor cell lines with telomerase deficiency achieved via the expression of dominant-negative hTERT mutant." (PMID 37176041, 2023). "The expression of HMGB2 was significantly associated with primary tumor size, invasion (infiltration depth) and FIGO stage (P < 0.05, respectively)." (PMID 33407071, 2021). "Many of these proteins interact with HMGB1 and HMGB2 whose overexpression is linked to tumor progression, metastasis and poor prognosis." (PMID 34680291, 2021). "We demonstrated that strong HMGB2 expression was associated with more aggressive tumor features and reduced OS and DFS in patients." (PMID 29463261, 2018). "Furthermore, HMGB2 drives the recruitment of tumor-associated macrophages (TAMs), MDSCs, and Tregs, promoting an immunosuppressive TME via RAGE and TLR4 signaling." (PMID 40396172, 2025). "Additionally, HMGB2, which was notably overexpressed in T1, has been linked to poor prognostic outcomes in various malignancies, facilitating tumour cell proliferation and invasion through the p38 MAPK signalling pathway." (PMID 40099956, 2025). "The combined approach of targeting HMGB2 and cell cycle regulators like Palbociclib may offer a new avenue for treating cancers, particularly those where HMGB2 is implicated in tumor progression and immune evasion." (PMID 40396172, 2025). "Furthermore, in the TCGA-LIHC cohort, the expression of HMGB2 significantly increased with tumor grade, suggesting a potential association with tumor aggressiveness." (PMID 39247201, 2024). "HMGB1 and HMGB2 have been implicated in numerous cellular processes including proliferation, differentiation, DNA replication, recombination, repair, transcription, inflammation, tumor migration, and cell signaling." (PMID 33178199, 2020). "HMGB2 plays a key role in tumor metabolic reprogramming by promoting aerobic glycolysis (Warburg effect) over oxidative phosphorylation." (PMID 40396172, 2025). "Together, these findings demonstrate that HMGB2 knockdown significantly inhibits cancer cell proliferation across a range of female-specific cancers, highlighting its critical role in tumor growth and suggesting its potential as a therapeutic target." (PMID 40396172, 2025). "HMGB2 plays a critical role in immune escape by modulating the tumor immune microenvironment (TME) and enhancing immune checkpoint pathways." (PMID 40396172, 2025). "The combination of Hmgb2-cKO mice and PD-1 antibody maximally inhibited the tumor growth and prolonged the survival time." (PMID 40315321, 2025). "Our study revealed distinct cellular compositions and varying degrees of malignancy across different tumour regions, with the T1 region showing the highest malignancy and overexpression of HMGB2 and TOP2A." (PMID 40099956, 2025). "To investigate the effect of HMGB2 knockdown on tumor cell proliferation in the presence of Palbociclib, we conducted CCK8 assays on multiple cancer cell lines." (PMID 40396172, 2025). "This suggests that targeting HMGB2, in combination with cell cycle inhibitors such as Palbociclib, can effectively suppress tumor cell growth." (PMID 40396172, 2025). "In GSE149614 dataset, HMGB2 expression was relevant with advanced tumor staging and was enriched in the tumor region." (PMID 40315321, 2025). "S10, D to F), we inferred that enhancement of T cell chemotactic activity depended merely on chemokines released by tumor cells after HMGB2 silencing." (PMID 40315321, 2025).
tumor (continued). "Second, HMGB2 activates the NF-κB signaling pathway, which increases glycolytic efficiency and provides energy for tumor cell proliferation and survival." (PMID 41220952, 2025). "Future research should address these by using animal models to explore the role of HMGB2 in tumor progression and metastasis." (PMID 40396172, 2025). "The effects were particularly pronounced in highly metastatic cell lines like MDA-MB-231 and SKOV3, underscoring HMGB2’s role in promoting tumor aggressiveness." (PMID 40396172, 2025). "Genetic disruption of HMGB2 showed that it regulates the trade-off between proliferative and invasive states, in which confined HMGB2high tumour cells are less proliferative but more drug-resistant." (PMID 40866703, 2025). "In an in vitro co-culture assay, we further confirmed that HMGB2-deficient NK cells showed enhanced killing ability on a variety of ESCC cell lines, especially in poorly differentiated tumor cells such as KYSE70 and KYSE150." (PMID 41280896, 2025). "Then, using an orthotopic HCC model in immunocompetent mice, we demonstrated that Hmgb2 knockdown in tumor cells combined with PD-1 antibody effectively reduced tumor burden and extended survival time." (PMID 40315321, 2025). "This study offers important insights into the molecular mechanisms driving female-specific cancers by elucidating the pivotal role of phagocytosis regulators, particularly HMGB2, in tumor progression." (PMID 40396172, 2025). "Its knockdown enhances sensitivity to cell cycle inhibitors like Palbociclib, while combining HMGB2 inhibition with glycolysis inhibitors reduces tumor viability." (PMID 40396172, 2025). "Regarding tumor cells, HMGB2 facilitated the transcriptional inhibition of Stat1 by TRIM24, thereby inactivating the interferon response and reducing the susceptibility and recruitment to effector cells." (PMID 40315321, 2025). "HMGB2 knockdown significantly inhibited these malignant phenotypes, suggesting its potential as a therapeutic target and a key driver of tumor progression." (PMID 40396172, 2025). "Elevated expression of HMGB2 correlates with tumor progression and NK cell dysfunction in ESCC patients, highlighting its potential role as a biomarker for disease staging." (PMID 41280896, 2025). "In 40 HB samples, HMGB2 expression was significantly higher in embryonal‐type tumours compared to other pathological types." (PMID 40099956, 2025). "In invading tumour cells, HMGB2 was only upregulated in elongated or misshaped tumour cells that appeared to be under mechanical pressure from adjacent tissues, indicating that confinement induces HMGB2 upregulation." (PMID 40866703, 2025). "Cluster 13 was exclusively expressed in T1, and the highly expressed markers TOP2A, CENPF, TPX2 and HMGB2 are related to tumour proliferation and malignancy." (PMID 40099956, 2025). "HMGB2 drives tumor progression by regulating cell cycle checkpoints, metabolic pathways, and immune evasion mechanisms." (PMID 40396172, 2025). "Targeting HMGB2, combined with glycolysis inhibitors like 2-DG(2-deoxyglucose), has shown promise in reducing tumor progression and inducing energy stress in cancer cells." (PMID 40396172, 2025). "Combining HMGB2 inhibition with anti-PD-L1 therapies has been shown to restore T cell function and enhance anti-tumor immunity." (PMID 40396172, 2025). "Since Hmgb2 knockout within CD8+ T cells promoted IFN-γ secretion and Hmgb2 knockdown within tumor cells enhanced IFN-γ response, we reasoned that blocking HMGB2 resulted in positive feedback killing cycle between T cells and tumor cells." (PMID 40315321, 2025). "To explore the impact of HMGB2 knockdown combined with Palbociclib treatment on tumor cell proliferation, we conducted EdU fluorescence staining assays on multiple cancer cell lines." (PMID 40396172, 2025). "HMGB2 induces T cell exhaustion, impairing their ability to effectively recognize and eliminate tumor cells, thereby facilitating tumor metastasis." (PMID 41354099, 2025).
tumor (continued). "Tannic acid, a specific inhibitor of HMGB2, synergized with PD-1 antibody to attenuate tumor growth and reverse T cell exhaustion." (PMID 40315321, 2025). "IHC analysis demonstrated that tumour cell markers, including HMGB2, TOP2A, CENPF, and TPX2, were strongly expressed in T1, with HMGB2 showing higher expression than TOP2A." (PMID 40099956, 2025). "Collectively, HMGB2 facilitates uncontrolled tumor growth by maintaining cyclin-CDK activity and evading checkpoint mechanisms." (PMID 40396172, 2025). "HMGB2 promotes tumor metastasis by modulating T cell function and regulating metabolic reprogramming." (PMID 41354099, 2025). "Recently, some researchers have also revealed that HMGB2 gets involved in tumor occurrence and progression, with high expression in various malignant tumors, and also affects the prognosis of tumor patients to some extent." (PMID 39591457, 2024). "By elucidating the intricate interplay between HMGB2 and the tumor microenvironment, we provide a foundation for the development of precision medicine approaches tailored to the unique molecular characteristics of individual tumors." (PMID 39247201, 2024). "For these calculations, the upper quartile (percentile 75—p75 = 108) score was used as cut-off value for “high” versus “low” HMGB2 expression, as it represents roughly 50% of tumor cells with moderate intensity or 33% of tumor cells with strong intensity." (PMID 38672598, 2024). "High levels of HMGB2 correlate with the primary tumor size, invasion capacity, and the stage of tumor development." (PMID 37176041, 2023). "It has been reported that HMGB2 gene knockout can induce cell senescence and inhibit the growth of tumor cells." (PMID 37903974, 2023). "To assess the role of HMGB2 expression in CD8+ T cells on tumor control, we adoptively transferred 1 × 106 congenically marked WT or Hmgb2−/− P14 T cells into separate, congenically mismatched WT mice." (PMID 37704621, 2023). "Epithelial cells with higher UVRAG expression showed higher expression of tumor migration-associated genes (HN1, HMGB2, PCNA, and CBX5)." (PMID 37173968, 2023). "The results comfirmed a significantly higher level of HMGB2 expression in the tumor tissues than that in the adjacent alveolar tissues." (PMID 35962344, 2022). "The results showed that the expression of HMGB2 was dramatically elevated in tumor cells as compared to that in the normal alveolar cells." (PMID 35962344, 2022). "Further study in the patient-derived samples was conducted to explore the correlation between HMGB2 protein expression levels with tissue specificity, (tumor size-lymph node-metastasis) TNM stage, pathological grade, Ki-67 status, and overall survival." (PMID 35962344, 2022). "IHC assay revealed that knockdown of CENPU led to significantly deceased expression levels of CENPU, HMGB2 and ki-67 in tumor tissue." (PMID 34872447, 2021). "The expression of HMGB2 was markedly higher in CC than that in HSIL and N. High HMGB2 expression was significantly correlated with primary tumor size, invasion and tumor stage." (PMID 33407071, 2021). "Meanwhile, we validated that KTN1-AS1 overexpression enhanced the tumor growth and the depletion of KTN1-AS1 or HMGB2 repressed the tumor growth in the nude mice." (PMID 34461605, 2021). "By contrast, other genes, including COPS7A, TAPT1, PAPD4, C4orf3, and HMGB2, have a tumor suppressor effect, and their high expression levels characterize patients with a good survival potential." (PMID 32626751, 2020). "Metastasis and large tumor size are correlated with high telomerase activity and enhanced HMGB1 and HMGB2 levels, and shown to be associated with lower patient survival." (PMID 33076532, 2020). "We further use the HMGB2 antibody as a bait to carry out RNA immunoprecipitation (RIP) with cell extracts from the SW620 tumour cell lines." (PMID 32067238, 2020).